ANXA6 (annexin A6)
Diseases named in the same sentence as ANXA6 in open-access papers (continued):
Sharing a sentence is not in itself a finding about the gene and the disease.
cancer (62 papers, 2011 to 2025). A tumor composed of atypical neoplastic, often pleomorphic cells that invade other tissues. "ANXA6 has been reported to be closely associated with a variety of tumors and be involved in cancer cell growth, motility, invasion, and adhesion." (PMID 36998449, 2023). "The surfaces of the ANXA6+ cancer-associated fibroblasts isolated from patients with pancreatic ductal adenocarcinoma samples were abundant with CD9." (PMID 36826916, 2023). "Together, our novel findings indicate besides EGFR gene mutation, PTM of the EGFR-binding protein AnxA6 also functions pivotal roles in mediating cancer cell growth and EGFR inhibitor drug effect." (PMID 37528485, 2023). "Annexin A6, transported in the extracellular vesicles of cancer-associated fibroblasts (CAFs), promotes drug resistance in a mouse metastatic tumor model by mediating the activation of FAK/YAP pathway in cancer cells via integrin β1." (PMID 36407100, 2022). "Nevertheless, few studies demonstrated the association of ANXA6/exosomal ANXA6 and drug resistance in cancers." (PMID 34238922, 2021). "Human or zebrafish muscle and cancer cells rendered deficient for ANXA6 suffer from a defect of membrane repair." (PMID 34067866, 2021). "Among all the proteins, ANXA6 is considered to be closely associated with cancer progression, which is frequently observed in extracellular vesicles." (PMID 34676207, 2021). "The underlying mechanism included the transfer of exosomal ANXA6 from resistant cancer cells to sensitive cancer cells." (PMID 34238922, 2021). "In conclusion, resistant cancer cell-derived exosomes induced gemcitabine resistance via exosomal ANXA6, which was associated with the inhibition of EGFR ubiquitination and degradation." (PMID 34238922, 2021). "A complex containing LRP1, TSP1, and annexin A6 was recently identified as being produced by cancer-associated fibroblasts in pancreatic ductal adenocarcinoma." (PMID 33925464, 2021). "Annexin A6 is frequently found in exosomes, secreted by cancer cells, and, depending on the cancer types, has been ascribed varying functions, often associated with cell motility and invasiveness." (PMID 29462943, 2018). "Hence, AnxA6 has been implicated in many biological processes, closely associated with a variety of cancers." (PMID 38566133, 2024). "Poor prognosis in cancer patients has also been linked to overexpression of ANXA6." (PMID 37124542, 2023). "This evidence suggests that ANXA6 levels may reflect anti-cancer drug resistance associated with cholesterol metabolic adaptation." (PMID 37129645, 2023). "An emerging concept is that differences in the expression status of intracellular and/or extracellular pools of AnxA6 underlie, at least in part, the distinct phenotypic characteristics of cancer cells and consequently, their propensity to grow rapidly or to become invasive." (PMID 32784650, 2020). "This may be relevant in certain cancers where loss of AnxA6 correlates with tumorigenesis and a more malignant phenotype." (PMID 23341998, 2013). "The dysfunction of AnxA6, including protein expression abundance change and imbalance of post-translational modification, is tightly related to multiple cancers." (PMID 38566133, 2024). "Our finding of AnxA6 decrease in EMT was consistent with the previous study on AnxA6 role in cancer cell migration." (PMID 38566133, 2024). "For instance, the CpG-rich AnxA6 promoter is heavily methylated in EGFR-overexpressing cancer cells with low AnxA6 levels." (PMID 38566133, 2024). "Meanwhile, we investigated the influence of K579-mediated SUMOylation of AnxA6 on protein function and cancer cell phenotype." (PMID 38566133, 2024). "Numerous previous studies have focused on AnxA6 biological role by tracking protein expression profiling with cancers." (PMID 38566133, 2024). "ANXA6 and membrane repair: Cancer cells can reach distant tissues through migration and invasive processes." (PMID 37129645, 2023).
cancer (continued). "ANXA6 is a potentially valuable marker in the diagnosis, progression, and treatment strategy of various cancers." (PMID 37129645, 2023). "AnxA6 displays cancer suppression effects on A431 cells by interacting with protein kinase Cα (PKCα) to reduce EGF-induced tyrosine phosphorylation of EGFR (pY-EGFR) and cycling D1 expression." (PMID 37528485, 2023). "Apart from drug and environment induced elevation of ANXA6, extracellular vesicles rich in ANXA6 can also be transferred from gemcitabine-resistant TNBC cells to sensitive cancer cells to increase ANXA6 expression." (PMID 37129645, 2023). "Some literatures have demonstrated that ANXA6 is involved in cell growth, differentiation, invasion, and motility in many cancers." (PMID 36998449, 2023). "These evidences suggest that ANXA6 is differently expressed in many cancers and shows a high potential value in the diagnosis, prognosis, and treatment strategies of various cancers." (PMID 37129645, 2023). "Indeed, our findings partly support this conclusion that AnxA6 SUMOylation enhances gefitinib efficacy to reduce A431 cell growth and migration, which indicates that AnxA6 SUMOylation may be an underlying novel mechanism for the EGFR-TKI resistance in many cancers." (PMID 37528485, 2023). "Upregulation of exosomal-ANXA6 (ANXA6-exo) enhances cell viability and colony formation and inhibits apoptosis in sensitive cancer cells." (PMID 37129645, 2023). "The scaffolding and auxiliary functions of ANXA6 inhibition of oncogenic signaling cascades are potentially valuable for malignant tumor development." (PMID 37129645, 2023). "Several review articles from our group and others have extensively covered AnxA6-related aspects relevant to cancer growth and metastasis." (PMID 35806209, 2022). "Much effort has been devoted over the past decade in extensively highlighting the tumorigenic properties of AnxA6 in several cancer types, as well as in the resistance of TNBC to EGFR-TKIs." (PMID 35267416, 2022). "Over the last decade, the tumorigenic properties of AnxA6 have been amply described in several cancer types, as well as in the resistance of TNBCs to EGFR-TKIs." (PMID 36230969, 2022). "In regard to the potential of AnxA6 levels as a marker to predict cancer recurrence and chemotherapy response, its downregulation sensitized TNBC cells to EGFR-TKIs and was associated with poorer overall and distant metastasis-free survival." (PMID 35806209, 2022). "Chemotherapeutic agents have been reported to stimulate the secretion of EVs containing various biologically active substances, such as ABCB1, annexin A6, miR-9-5p, miR-203a-3p, and miR-195-5p, promoting chemoresistance and cancer invasiveness." (PMID 35326493, 2022). "Previous work and data presented here, using genetic and pharmacological NPC1 inhibition or AnxA6 overexpression, demonstrated that blocking LE-Chol export interfered with the migratory, but also invasive behaviour of several cancer cell lines." (PMID 35022465, 2022). "These opposing activities probably relate to the multiple and diverse AnxA6 scaffolding functions, which are likely to differ in the various cancer cells due to the different repertoire and availability of interaction partners." (PMID 33810523, 2021). "The present study managed to investigate this issue and found that ANXA6-exo promoted PTX resistance and cancer progression in BC cells in a Yes-associated protein 1 (YAP1)-dependent manner." (PMID 34676207, 2021). "In the present study, we revealed that exosomal ANXA6 derived from chemoresistant cancer cells induced gemcitabine resistance by inhibiting the ubiquitination and degradation of EGFR." (PMID 34238922, 2021). "Annexin A6 (ANXA6) is a superfamily member of membrane-binding annexin proteins, and it has been reported that the expression level of ANXA6 is closely correlated with various cancers." (PMID 34124058, 2021).
cancer (continued). "TSP1 is associated with EVs released by cancer-associated fibroblasts via a complex that includes LRP1 and annexin A6." (PMID 33925464, 2021). "Sensitive cancer cells exhibited resistance with increased viability and colony formation and decreased apoptosis when ANXA6 was stably overexpressed." (PMID 34238922, 2021). "Isobaric peptide labeling–liquid chromatography–tandem mass spectrometry and western blotting revealed that ANXA6 was upregulated in resistant cancer cells and their derived exosomes." (PMID 34238922, 2021). "Among all the cancer-associated genes, annexin-A6 (ANXA6) is a multifunctional intracellular scaffolding protein that is frequently detected in extracellular vesicles and is closely associated with cancer progression and drug resistance." (PMID 34676207, 2021). "Our results revealed that exosomal ANXA6 derived from gemcitabine-resistant cancer cells interacted with EGFR and induced gemcitabine resistance by inhibiting EGFR ubiquitination and degradation." (PMID 34238922, 2021). "ANXA6 or Atg7 knockdown stimulated cancer cell proliferation to a greater extent than wild‐type cells based on the results of cell growth curves and colony formation assays." (PMID 33135350, 2020). "Though recent studies have revealed that the expression of ANXA6 is bound up with chemoresistance and poor prognosis of malignant tumors, its role in radioresistance in various kinds of tumors has not yet been reported." (PMID 32373608, 2020). "In that position, ANXA6 can contribute to many different processes including cancer cell migration and invasion." (PMID 31784980, 2020). "WIPI2 overexpression significantly inhibited cancer cell colony formation, but ANXA6 knockdown weakened the suppressive effect of autophagy induction." (PMID 33135350, 2020). "The abundance of AnxA6 in serum and cell-derived EVs also provides an opportunity to predict cancer metastasis in breast and other cancer types." (PMID 32784650, 2020). "The potential usefulness of AnxA6 as a biomarker for the severity of certain cancer types has also been extensively reported." (PMID 32784650, 2020). "The calcium (Ca2+)-dependent membrane-binding Annexin A6 (AnxA6), is a multifunctional, predominantly intracellular scaffolding protein, now known to play relevant roles in different cancer types through diverse, often cell-type-specific mechanisms." (PMID 32784650, 2020). "While these studies are in strong support for a critical role of AnxA6 in cancer metastasis, this also suggests that AnxA6 enrichment in EVs can be targeted for therapeutic purposes." (PMID 32784650, 2020). "A strictly different behavior was observed in damaged MCF-7 cancer cells, in which AnxA6-GFP is recruited to wound edges where it promotes the closure of the hole by triggering contraction of the membrane edges." (PMID 32708200, 2020). "Annexin A6 enriched tumor-derived Evs secreted from cancer cells treated with chemotherapeutic compounds taxanes and anthracyclines were found to promote cancer metastasis to lung by inducing the activation of NFκB and CCL2." (PMID 32010626, 2019). "The role of annexin A6 in cell repair leading to resistance of cancer cells to liprotide-induced permeabilisation was confirmed in MCF7 cells, where a knockdown of this annexin significantly increased liprotide cytotoxicity." (PMID 29462943, 2018). "In several types of cancer, AnxA6 acts via Ras, Ras/MAPK and/or FAK/PI3K signalling pathways, by mainly mediating PKCα, p120GAP, Bcr-Abl, and YY1." (PMID 29462943, 2018). "Two opposing notions have thus far emerged from several studies on the potential functions of AnxA6 in cancer progression." (PMID 24354805, 2013). "In MicSCC, expression of ANXA6 was positive in cancer cells in seven (77.8%) cases showing presence of sporadic ANXA6+ cells." (PMID 21119665, 2011). "Cleavage of the NH2-domain severely impairs the function of ANXA6, while full-length ANXA6 is generally described to be under expressed in cancer and during carcinogenesis." (PMID 21119665, 2011).
cancer (continued). "There is growing evidence that epigenetic silencing of AnxA6 is a common mechanism in cancers." (PMID 38566133, 2024). "Nevertheless, ANXA6 showed the opposite effect on several cancers." (PMID 37129645, 2023). "The information reviewed in this article may expand researchers’ understanding of ANXA6 and contribute to the future development of ANXA6-based treatment strategies for cancer patients." (PMID 37129645, 2023). "And AnxA6 is also a potential candidate target for antibody-mediated inhibition of cancer." (PMID 37528485, 2023). "Thus, ANXA6 is related to many cancer-related biological processes, including vesicular transport, cell proliferation and division, apoptosis, calcium signaling, and growth regulation, among many other cellular functions." (PMID 37129645, 2023). "The specific intracellular and extracellular scaffolding functions of ANXA6 and its interacting proteins may contribute differently to various cancers’ progression and treatment outcomes." (PMID 37129645, 2023). "ANXA6 can even be used to predict cancer recurrence and chemotherapy response." (PMID 37129645, 2023). "However, which kind of PTMs on AnxA6 and how to regulate biological process are rarely known in cancer cells." (PMID 37528485, 2023). "Next, we clarified biological function of AnxA6 in cancer cell proliferation and migration." (PMID 37528485, 2023). "We next evaluated whether AnxA6 co-operated with gefitinib to inhibit cancer cell proliferation and migration." (PMID 37528485, 2023). "Research on the function of ANXA6 mainly concentrate on many cancers." (PMID 35456441, 2022). "The involvement of ANXA6 in plasma membrane repair may allow cancer cells to rapidly respond to small membrane injuries that arise frequently, as demonstrated in MCF-7 cells." (PMID 36247003, 2022). "ANXA6 has been involved in several biological processes such as cell proliferation, survival, membrane repair, migration and adhesion, which are often dysregulated in cancer." (PMID 36247003, 2022). "ANXA6 expression has been proposed as a useful biomarker in several human cancers." (PMID 36247003, 2022). "Involvement of ANXA4 in membrane repair has been mainly studied in cancer cells, where accumulated as trimers at the damaged area it induces invagination of edges of the disruption site in order to facilitate constriction of the tear by ANXA6." (PMID 34067866, 2021). "In fact, the potential of ANXA6 as a biomarker for cancer has been previously investigated." (PMID 34238922, 2021). "ANXA6 is selectively enriched in cancer-originated exosomes." (PMID 34238922, 2021). "The role played by AnxA6 in the processes of membrane repair may therefore be different in human skeletal muscle and cancer epithelial cells." (PMID 32708200, 2020). "Whether the description of mechanisms related to membrane resealing in cancer cells was outside the scope of this study, some observations that we have done gave interesting clues on the role played by AnxA5 and AnxA6." (PMID 33311633, 2020). "Regarding human cells, the rapid recruitment of Anx in a tight structure, which may look like a cap subdomain, has been observed for AnxA5 in skeletal muscle cells and AnxA4 and AnxA6 in cancer epithelial cells." (PMID 32708200, 2020). "Here, we review our current knowledge on the role of AnxA6 in cancer progression." (PMID 32784650, 2020). "While the list of AnxA6 interacting proteins and/or protein complexes is not yet exhaustive, it is possible that the discovery of novel interacting proteins and the relationship with AnxA6-mediated functions will provide a further premise for its multiple functions in cancer." (PMID 32784650, 2020). "Accumulating evidence suggests that the multifunctional role of AnxA6 in cancer may largely depend on its multiple and diverse scaffolding functions." (PMID 32784650, 2020). "In these cancer epithelial cells, Nylandsted and collaborators have shown that AnxA6 induces membrane curvature, which may facilitate membrane resealing." (PMID 32708200, 2020).
cancer (continued). "Here, we review our current understanding of the potential of AnxA6 as a biomarker for cancer diagnosis, the poor response of TNBC to EGFR-targeted therapies, and the prospects for the detection of AnxA6 as a predictor of the response of TNBC to EGFR-targeted therapies." (PMID 32784650, 2020). "Previous studies have showed a low expression of annexin a6 in many cancer types." (PMID 31877708, 2019). "Inhibiting annexin A6 in Evs from cancer cells significantly reduced cancer metastasis." (PMID 32010626, 2019). "The pathway analysis also revealed that changes in the expression status of AnxA6 affects cellular processes that are important in cancer progression such as the regulation of cell cycle progression, DNA damage response, energy metabolism, oxidative stress, apoptosis and senescence and autophagy." (PMID 30719209, 2019). "Thus, ANXA4 and ANXA6 improve cells' ability to cope with stress-induced plasma membrane disruptions, which appears to be a strategy used by cancer cells to counteract frequent membrane injuries." (PMID 29158488, 2017). "Annexin A6 was first identified in the matrix vesicles of chicken growth plate cartilage, and recent research has documented Annexin A6 expression in a wide range of mammalian tissues, including skeletal muscle, heart, and spleen and in some cancer cell lines." (PMID 22984583, 2012). "We previously suggested that this observation represents nuclear expression of ANXA6 in cancer cells, however, because of the variable histopathological appearance we could not exclude the possibility that these were infiltrating immune cells." (PMID 21119665, 2011). "Appearance of ANXA6+ cells only between dysplastic and cancer cells was an interesting observation, which may improve diagnosis." (PMID 21119665, 2011). "However, the PTMs of AnxA6 are rarely understood in cancers so far." (PMID 38566133, 2024). "ANXA6 is a multifunctional scaffold for cell movement that links to a variety of proteins in the extracellular matrix and cytoskeleton, and the abnormal expression may impair membrane repair processes and cancer metastasis." (PMID 37129645, 2023). "These evidences suggest that ANXA6 may influence cancer therapy through membrane repair mechanisms." (PMID 37129645, 2023). "However, there are few studies on ANXA6 in tumors, and its mechanism of action in many cancers still remains unclear." (PMID 37129645, 2023). "However, it is unknown how AnxA6 participates in FSS-induced autophagy during osteogenic differentiation, even though the contribution of AnxA6 to autophagy during cancer progression was confirmed." (PMID 36555344, 2022). "It has been demonstrated that ANXA6 present in extracellular vesicles may play a role in cancer." (PMID 36247003, 2022). "However, our understanding of how AnxA6 promotes the progression of TNBC as well as a very diverse set of other cancers remains largely unknown." (PMID 32784650, 2020). "Loss of ANXA6 has been reported to destabilize the ANXA6/low-density lipoprotein receptor-related protein 1 (LRP1)/thrombospondin-1 (TSP1) complex, which leads to reduced uptake of CAF-derived exosomes by cancer cells, and a reduction in their proliferative and migratory abilities." (PMID 32957712, 2020). "AnxA6 may therefore act differently in cancer epithelial MCF-7 and muscle LHCN cells." (PMID 32708200, 2020). "Significant differences in protein levels were also observed between benign and malignant tumors, for example, the up‐regulation of Translocation protein SEC63 homolog, Annexin A6 and Biglycan in CXPA compared to PA." (PMID 39155517, 2025). "Compared with the corresponding adjacent non-cancer tissues, the level of SENP1 and RHOU was upregulation in HCC tissues, but AnxA6 level was downregulation." (PMID 38566133, 2024).